CD4 (CD4 molecule)
Diseases named in the same sentence as CD4 in open-access papers (continued):
Sharing a sentence is not in itself a finding about the gene and the disease.
asthma (continued). "Naïve CD4 T cells (CD4+CD45RA+CD45RO−) were magnetic beads sorted from the peripheral blood of asthma patients and then cultured under appropriate polarizing conditions to generate Th1 and Th2 cells." (PMID 34126986, 2021). "Dental follicle MSCs inhibited the proliferation of CD4+ T cells and reduced effector and effector memory CD4+ T cell numbers in a mouse asthma model." (PMID 34635172, 2021). "Analogous to GSDMA, GSDMB is also linked to childhood‐onset asthma, while GSDMB (rs9303277) in CD4+ T cells is an SSc‐associated susceptibility locus." (PMID 34459122, 2021). "Patients with acute pneumonia, stable pneumonia, acute asthma or stable asthma contained a small frequency of CD4+ Tex cells, with the large majority being activated CD4+ T cells." (PMID 34841705, 2021). "Asthma is driven by group 2 innate lymphoid cells, antigen-specific CD4+ T helper type 2 cells and their cytokines such as interleukin (IL)-4, IL-5, IL-13." (PMID 34516405, 2021). "Futhermore, while T lymphocytes, specifically CD4+T-cells play a major role in the pathophysiology of asthma, particularly eosinophilic and CS-responsive asthma, CD8+ T cells are important effector cells in the pathogenesis of severe CS-resistant asthma." (PMID 34777398, 2021). "We calculated NPV and PPV for API and CD4+CCR6+CRTH2+ memory Th2 cells level in predicting asthma diagnosis." (PMID 34090369, 2021). "In conclusion, the present study suggests that the observed differences in the frequencies of allergen-responsive Foxp3 or IL-10 CD4 T cells are associated with the distinct susceptibility of A/J, BALB/c, and C57BL/6 mice to experimental asthma." (PMID 34924814, 2021). "To determine the role of T cell-specific GRK2 in affecting the asthma pathology, we generated a mouse stain [CD4 Cre+ GRK2fl/fl (Cre+)] that lacks GRK2 in T cells." (PMID 35386975, 2021). "Both conventional CD4+ T cells and innate-like invariant Natural Killer (iNKT) cells have been shown to be involved in asthma in humans and mouse models." (PMID 34061861, 2021). "CD4+CD25+FoxP3+Tregs have been confirmed to play a pivotal role in allergic diseases such as asthma, hay fever, and allergic rhinitis." (PMID 33954205, 2021). "have reported that ZFP36L2 expression in peripheral blood CD4+ T cells is significantly higher in severe asthma patients than in mild asthma patients." (PMID 34276705, 2021). "We also found the increased MBD2 expression after stimulus differentiation in splenic CD4+ T-cells in our animal model, showing involvement of MBD2 in immunological pathogenesis of Th17 mediated neutrophilic severe asthma and differentiation of CD4+ T-cells." (PMID 35096261, 2021). "Proliferation of CD4+ T-lymphocytes has been observed in children with asthma and proliferation of Th17 cells has been found to be increased in non-eosinophilic neutrophilic asthma." (PMID 34721414, 2021). "Naïve CD4 T cells from patients with asthma were cultured under appropriate polarizing conditions to generate Th1 and Th2 cells." (PMID 34126986, 2021). "Logistic regression analysis further indicated that CD4+CCR6+CRTh2+ memory Th2 cells and wheezing frequency were the independent risk factor for the outcome of asthma diagnosis." (PMID 34090369, 2021). "Asthma is a complex and heterogeneous inflammatory response characterized by various immune cells, including myeloid-derived suppressor cells (MDSCs) and CD4+ T-cell subsets." (PMID 32549755, 2020). "In the context of asthma, anti-LFA-1 and anti-ICAM-1 were shown long ago to be beneficial in experimental asthma through effects on CD4+ T-cells." (PMID 33193309, 2020). "Vitamin A supplement after neonatal S. pneumoniae pneumonia inhibits the progression of experimental asthma by altering CD4+T cell subsets productions." (PMID 32144294, 2020). "Type 2 cytokine production by TH2 polarized iNKTs and other CD4+ T cells make them significant players in asthma pathogenesis." (PMID 32733448, 2020).
asthma (continued). "Our data indicated that neonatal S. pneumoniae pneumonia induce serum vitamin A deficiency and long-time lung vitamin A reduction, vitamin A supplement after neonatal S. pneumoniae pneumonia inhibit the progression of asthma by altering CD4+T cell subsets." (PMID 32144294, 2020). "MiRNAs potentially sponged by PVT1 were predicted with usage of starbase software, and asthma-relevant miRNAs were measured in CD4+ T cells and ASMCs isolated from mice models." (PMID 33223504, 2020). "In this study, we tested the possibility of treating asthma by controlling the differentiation of CD4+ T cells via DC activation as an alternative to conventional asthma therapy." (PMID 32143368, 2020). "Studies have shown IFNγ+ CD4+ T cells are more prevalent in the airways in severe asthma versus mild, moderate disease and that IFNγ-induced expression of CXCL10 and down-regulation of SLPI lead to increased AHR and steroid resistance in severe asthma." (PMID 33101299, 2020). "Lymphocytes, in particular CD4+ Type-2 lymphocytes, play a crucial role in the pathogenesis of asthma." (PMID 32570774, 2020). "In inflammatory contexts, such as asthma, CD4+ T cells can play into both TH17 and TH2 type mediated inflammation and have also been shown to utilize autophagy." (PMID 32733448, 2020). "The specific role and relationship of MDSCs with other immune cells, especially CD4+ T cells, in asthma are rarely reported." (PMID 32549755, 2020). "CD4+ T cells play a crucial role in the control asthma-related inflammation and are the predominant lymphocytes that infiltrate airways." (PMID 32143368, 2020). "There were 118 subjects with gene expression data passing quality control from CD4+ lymphocytes in Asthma BRIDGE who reported taking inhaled corticosteroids as a controller medication in the previous year." (PMID 31992292, 2020). "Asthma is an inflammatory disease of the lung airway network, which is initiated and perpetuated by allergen-specific CD4+ T cells, IgE antibodies, and a massive release of Th2 cytokines." (PMID 33267824, 2020). "Schistosome soluble egg antigen (SEA) from S. japonicum showed inhibitory effects on the development of airway inflammation in a CD4+ CD25+ T cell–dependent manner during OVA-induced asthma in mice." (PMID 33013887, 2020). "The amelioration of OVA-induced asthma by PAS-1 was mediated by IL-10/TGF-β–producing Treg cells (CD4+CD25+) and IFN-γ–producing CD8+ T cells." (PMID 33013887, 2020). "Oral Bifidobacterium breve MRx0004, a commensal strain isolated from a healthy person, reduced the immunopathology of peribronchiolar and perivascular, and increased lung CD4+FoxP3+ cells in a murine model of severe asthma." (PMID 32431609, 2020). "Our data suggest that neonatal S. pneumoniae pneumonia induce serum vitamin A deficiency and long-time lung vitamin A reduction, vitamin A supplement after neonatal S. pneumoniae pneumonia inhibit the progression of asthma by altering CD4+T cell subsets." (PMID 32144294, 2020). "Children with a diagnosis of asthma had an increased percentage of type 2 T cells identified as CD4+CCR4+, which demonstrated increased activation of STAT5 following stimulation with 100 U/ml IL-2 for 10 min." (PMID 32985505, 2020). "In our initial studies, libraries prepared out of CD4+ T cells from the asthma cohort were used for the RNA sequencing analysis." (PMID 32317758, 2020). "Biased differentiation of CD4+ T cells into Th1-like and Th2-like cells was also responsible for abnormal inflammation in asthma." (PMID 33223504, 2020). "In people with mild to moderate asthma, there is predominant accumulation of eosinophils and CD4+ cells that produce Th2 cytokines in the lungs and high concentration of serum IgE." (PMID 33123138, 2020). "We used gene expression data from CD4+ lymphocytes in the Asthma BioRepository for Integrative Genomic Exploration (Asthma BRIDGE), an open-access collection of subjects participating in genetic studies of asthma with available gene expression data." (PMID 31992292, 2020).
asthma (continued). "Contact between airway smooth muscle cells and activated CD4+ T cells is a key interaction in diseases such as asthma, that operates in both directions." (PMID 32317758, 2020). "In particular it will be of interest to identify if an ASM- CD4+ -T-cell communication axis driven by WNT5A-IL31 signaling underpins remodelling of the ASM bundle in asthma." (PMID 32317758, 2020). "Classical asthma is eosinophilic with increased number of CD4+ T cells that produce Th2 type cytokines." (PMID 31277695, 2019). "Precisely, the last subset is expanded in both groups of asthma patients: AA (CD4+ Tlow cells) and NAA (γδ-T cells)." (PMID 31101830, 2019). "Our data show that cells resisting FTY720 and anti-CD4 are retained in the lungs and mediate disease, which agrees with other studies in mice and clinical studies demonstrating little benefit of anti-CD4 treatment in severe asthma." (PMID 31105692, 2019). "To assess the association between CD15+ Treg cells and asthma, we compared the proportion of sialyl LeX positive FOXP3+ Treg cells among CD4+ T cells between intermittent-to-mild (n = 20) and moderate-to-severe (n = 11) asthma and healthy controls (n = 19)." (PMID 31222115, 2019). "Asthma pathogenesis primarily involves activation of eosinophils and CD4+ T cells, with downstream inflammation mediated mainly by Th2-type cytokines (IL-3, IL-4, IL-5, IL-9, IL-13, and granulocyte macrophage colony-stimulating factor)." (PMID 30126769, 2019). "To obtain a global overview of CD4+ T cells in the asthma transcriptome, we constructed and sequenced 6 RNA-Seq libraries, including controls (n = 3) and asthma mice (n = 3)." (PMID 31231429, 2019). "IL-4, IL-13, and IL-21, which promoted Th2 differentiation and allergic asthma, were also significantly increased in the CD4+ T cells from the asthma mouse model." (PMID 31231429, 2019). "With respect to mRNAs, 141 mRNAs were significantly downregulated and 160 mRNAs were significantly upregulated in the CD4+ T cells from asthma." (PMID 31231429, 2019). "Consistently, an increased frequency of IL-21-expressing CD4+ T cells is also observed in asthma patients." (PMID 31921177, 2019). "ST2+ memory CD4+ T cells have the capacity to produce high levels of IL-5 and Amphiregulin and are involved in the pathology of asthma." (PMID 30972065, 2019). "On the contrary, the proportion of sialyl LeX positive FOXP3+CCR7+CCR4− Treg cells among CD4+ T cells was lower in moderate-to-severe asthma compared with healthy controls (post hoc p < 0.05)." (PMID 31222115, 2019). "CD4+ T cells play a crucial role in the pathogenesis of asthma and can be activated to differentiate into Teff lymphocytes." (PMID 30873032, 2019). "Modified HMW-HA also interacts with CD44 to inhibit NF-κB activation, dendritic cell maturation, and allergen-specific CD4 T-helper reaction, potentially providing therapeutic effects to asthma and allergic sinusitis." (PMID 31067702, 2019). "In our study, we identified 134 lncRNAs and 301 mRNAs abnormally expressed in CD4+ T cells of asthma compared with controls." (PMID 31231429, 2019). "Although long non-coding RNAs (lncRNAs) have been linked to many diseases including asthma, little is known about lncRNA transcriptomes of CD4+ T cells in asthma." (PMID 31231429, 2019). "In human studies, our group and other groups have found significantly higher circulating TFH cell (CXCR5+CD4+) levels in both child and adult asthma patients in comparison with healthy cohorts." (PMID 31921177, 2019). "Because of their myriad effects on inflammatory responses in the respiratory tract, CD4+ T cells have been identified as potent regulators of asthma pathogenesis." (PMID 31921177, 2019). "Previously, adoptive transfer experiments demonstrated that peripheral CD4+ T lymphocytes regulate asthma pathogenesis." (PMID 31231429, 2019).
asthma (continued). "In particular, the pivotal roles of delta isoform of class I PI3Ks (PI3K-δ) in CD4-positive type 2 helper T cells-dominant disorders such as asthma have been consistently reported since the early investigations." (PMID 31323822, 2019). "Our results from an asthma model using IL-31RA KO mice showed that IL-31R signaling negatively regulates inflammation through suppressing the proliferation of CD4+ T cells, which led to the decreased production of Th2-type cytokines." (PMID 30647024, 2019). "The treatment increased the percentage of FoxP3+ T cells within CD4+ T cells significantly, from about 40% to about 65%; thus, the GCs did induce an increase in the Treg subset in the equine asthma model." (PMID 30845709, 2019). "In conclusion, we conducted a comprehensive analysis of lncRNA profiles in CD4+ T cells from an asthma model using next-generation sequencing." (PMID 31231429, 2019). "Different from the sequencing data, the expression of LncRNA fantom3_4933428M03 or fantom3_F630107E09 was unexpectedly similar in the CD4+ T cells from either the asthma or the control group." (PMID 31231429, 2019). "CD4+ T cells from the asthma group showed higher expression of the Th2 master transcription factor Gata-3 and decreased expression of the Th1 master transcription factor T-bet." (PMID 31231429, 2019). "We also compared the proportion of sialyl LeX positive FOXP3+ Treg cells among total CD4+ T cells, and found that it was slightly lower in asthma children compared with healthy controls (p = 0.16), despite not reaching statistical significance." (PMID 31222115, 2019). "To further examine the function of these differentially expressed lncRNAs in CD4+ T cells in asthma, we constructed an lncRNA-mRNA co-expression network between 301 differentially expressed mRNAs and 23 differentially expressed lncRNAs." (PMID 31231429, 2019). "Next generation sequencing for lncRNAs and mRNAs was performed on CD4+ T cells from asthma and control mice." (PMID 31231429, 2019). "Using real-time qRT-PCR, we demonstrated that lncRNA fantom3_9230106C11 was decreased in CD4+ T cells from asthma mice ex vivo and in Th2 cells in vitro." (PMID 31231429, 2019). "Th2-type CD4+ T cells secrete IL-4, IL-5, and IL-13, which play important downstream roles in asthma pathogenesis." (PMID 29507584, 2018). "It has been reported previously that DC10 treatments reverse the disease phenotype in OVA and house dust mite models of asthma, wherein they suppress the allergen-specific T cell response, inducing Th2 cells to differentiate into CD4+CD25+Foxp3+ Treg." (PMID 29293622, 2018). "In our study, HIF-1α expression increased in mouse splenic CD4+ T cells and lung tissues in both the neutrophils-dominant asthma and conventional asthma groups, but this was more significant in the neutrophils-dominant asthma group." (PMID 30150897, 2018). "In a mouse asthma model of asthma, infusing CD4+ CD25+ Tregs can alleviate airway inflammation and airway hyperresponsiveness through increasing the serum level of IL-10." (PMID 30089474, 2018). "Immunological memory is critical for long-standing protection against microorganisms; however, certain antigen-specific memory CD4+ T helper (Th) cells drive immune-related pathology, including chronic allergic inflammation such as asthma." (PMID 29951134, 2018). "In mice, the adoptive transfer of CD9+ B cells reverses asthma, and the adoptive transfer of CD1dhi Bregs suppresses airway inflammation by inducing natural forkhead box protein 3-positive CD4+ regulatory T cell recruitment into the lungs." (PMID 30622536, 2018). "MBD2 expression in lung and splenic CD4+ T cells from the neutrophils-dominant asthma group were significantly increased compared to the conventional asthma group." (PMID 30150897, 2018). "Our previous work indicates that, compared to healthy volunteers, MBD2 and HIF-1α expression in CD4+ T cells was increased in the peripheral blood of patients with asthma." (PMID 30150897, 2018).
asthma (continued). "Glucocorticoid hormones do not alter differentiation and responsiveness of Th17 cells, though the major subtype of effector lymphocyte involved in the pathogenesis of severe asthma is the CD4 T cells." (PMID 29849493, 2018). "The exact mechanism of phenotypes of asthma in with obesity have been questioned to involve TH2 cytokines as CD4+ cells are important in asthma inflammation." (PMID 30631374, 2018). "The frequency and absolute numbers of CD4+ T-cells were also significantly reduced in the lungs of Bcl11bfl/fl dLck-iCre mice induced with HDM-asthma." (PMID 29700302, 2018). "The percentage of CCR4+ in CD4+ T cells was significantly different between control subjects and patients with severe asthma based on the % predicted FEV1 (left)." (PMID 29507584, 2018). "The authors concluded that CD4+CD25+ TRegs are critical for maintaining self-tolerance, and are associated with moderate to severe asthma." (PMID 31826046, 2018). "In murine models of asthma, CD4+ T-helper cells in the lungs and bronchoalveolar lavage fluid decrease eosinophilia and the Th2 cytokine secretion of IL-4, IL-5, IL-13, and TGF-β." (PMID 29959403, 2018). "In both murine models of allergic asthma and asthma patients, CD4+ memory T cells are involved in recurrent episodes of inflammation." (PMID 29507584, 2018). "The CD4+ T cell is a dominant activated T cell subtype in clinical allergic asthma and in animal models of asthma, an mainly contributes to AHR development and allergic inflammation by secreting Th2 cytokines such as IL-4, IL-5, and IL-13." (PMID 29910732, 2018). "Asthma is characterized by an expansion of CD4+ helper T lymphocytes (Th2, Th17), increased production of the Th2 cytokines IL-4, IL-5, and IL-13, an increased level of allergen-specific immunoglobulin E (IgE), eosinophilia and inflammation of the airways." (PMID 30622536, 2018). "Enhanced levels of CD4+ cells in murine models of asthma have also been shown to correlate with the LAR." (PMID 28399855, 2017). "When allergens or pathogens are inhaled, DCs are activated to prime CD4+ TH2 cell development to induce the TH2 atopic immune response characteristic of asthma." (PMID 29250125, 2017). "In this study, we assessed the contribution of C5a-C5aR to CD4+T cell immune responses in RSV-infected asthma mice." (PMID 29123203, 2017). "The CD4+ T cells [also referred to as T helper (Th) cells] play an important role in asthma pathogenesis." (PMID 28974953, 2017). "We report here that in asthma, Treg-mediated suppression strictly requires the coretention of induced antigen-specific asTregs and antigen-specific CD4+ T cells." (PMID 28638384, 2017). "In asthma patients the CD3+CD4+ T cells express more CD4 and the CD3+CD8+ T cells more CD8 compared to control individuals." (PMID 28710472, 2017). "The observed differences in the levels of several cytokines in equine asthma can most likely be explained by alterations in the CD4+ T cell development pathway." (PMID 29231896, 2017). "Elucidation of the C5a-C5aR activated by RSV infection and the contribution of C5a-C5aR to CD4+T cell immunity is of significance in RSV-induced asthma exacerbation." (PMID 29123203, 2017). "The primary inflammatory lesion of asthma is accompanied by the accumulation of cluster of differentiation 4+ (CD4+) Th2 cells and Eos’s in the airway mucosa and its secretion of a series of cytokines, mostly IL-4, IL-13, IL-5, and IL-9." (PMID 28678189, 2017). "We previously reported that bvPLA2 can induce Foxp3-expressing CD4+ regulatory T cells (Tregs) in OVA-induced asthma and acute kidney injury model." (PMID 28218721, 2017). "HDM allergens play a crucial role in the development of AR and asthma, and its allergenic effects are thought to be orchestrated through the CD4+ Th2 cells that drive the IgE-dependent allergic response." (PMID 28740493, 2017). "The objective of this study is to clarify the relationship between C5a-C5aR and CD4+T cells in RSV-infected asthma mice." (PMID 29123203, 2017).